TGFB3 (transforming growth factor beta 3)
Diseases named in the same sentence as TGFB3 in open-access papers (continued):
Sharing a sentence is not in itself a finding about the gene and the disease.
synovial chondromatosis (2 papers, 2015 to 2020). Synovial chondromatosis is a type of non-cancerous tumor that arises in the lining of a joint. "Moreover, relative studies had reported that fibroblast growth factor 2 (FGF-2) or transforming growth factor beta 3 (TGF-β3) were responsible for the formation of cartilaginous loose bodies and involved in the pathogenesis of synovial chondromatosis." (PMID 32534572, 2020).
alopecia (1 paper, 2011). Hair loss usually from the scalp. "Since Pofut1/Tgfb3-Cre mice displayed alopecia at the second hair cycle, we undertook a histological analysis on control and mutant mice at different stages of the hair cycle." (PMID 21267458, 2011). "In contrast, Pofut1/Tgfb3-Cre mice had an average life span of 4–5 months and exhibited progressive alopecia in a head-to-tail direction after 3 weeks postpartum." (PMID 21267458, 2011).
ameloblastoma (1 paper, 2020). The most common odontogenic tumor, arising from the epithelial component of the embryonic tooth and usually affecting the molar-ramus region of the mandible or maxilla. "We also found that expression levels of TGF‐β family genes, including TGFB1, TGFB3, and GDF15, significantly increased in ameloblastoma." (PMID 32096304, 2020). "Interestingly, we found that TGF‐β signaling‐related genes including transforming growth factor beta 3 (TGFB3), snail family transcriptional repressor 1 (SNAI1), and inhibitor of DNA binding 3 (ID3) were significantly activated in ameloblastoma tumors." (PMID 32096304, 2020).
Amoebiasis (1 paper, 2024). "While some significant GO terms were identified in female MIA offspring (‘Amoebiasis’, ‘Cytokine-cytokine receptor interaction’ and ‘Human T-cell leukemia virus 1 infection’), all were driven by the genes interleukin 1 receptor type 1 (Il1r1) and transforming growth factor beta 3 (Tgfb3)." (PMID 38715090, 2024).
aortic stenosis (1 paper, 2017). Aortic valve stenosis is a aortic valve disease caused by the incomplete opening of the aortic valve. "Cardiac CILP1 expression in the aortic stenosis patients was very strongly correlated to TGFβ3." (PMID 29167509, 2017).
aortic valve disease (1 paper, 2020). "TGFB3 mutations have also been reported in patients with mitral and aortic valve disease and that hyper-activated TGFβ signaling has been implicated in mammalian valve disease." (PMID 32456345, 2020).
atopic dermatitis (1 paper, 2011). "Interestingly, Pofut1/Tgfb3-Cre mice displayed splenomegaly and lymphoadenopathy around 3 weeks of age and developed full-blown atopic dermatitis-like disease in adult (data not shown)." (PMID 21267458, 2011).
atrial septal defect (1 paper, 2020). Interauricular communication is a congenital malformation characterized by a communication between the atrial chambers of the heart. "It is interesting that Tgfb3−/− fetuses have no atrial septal defects (ASD) and inflow tract abnormalities such as atrioventricular septal defects (AVSD), double inlet left ventricle (DILV), and common AV canal." (PMID 32456345, 2020).
autism (1 paper, 2024). Persistent deficits in social interaction and communication and interaction as well as a markedly restricted repertoire of activity and interest as well as repetitive patterns of behavior. "To determine whether altered expression of TGFB genes occurred before or after differentiation, we analyzed TGFB1, B2 and TGFB3 gene expression in the NSCs of patients with autism and control subjects." (PMID 38994948, 2024).
Cachexia (1 paper, 2017). Severe weight loss, wasting of muscle, loss of appetite, and general debility related to a chronic disease. "TGFβ1 and TGFβ3 levels were up-regulated by cachexia in AT, as well in the isolated adipocytes." (PMID 28288584, 2017).
cervical tumor (1 paper, 2019). "Proteins such as STAT3, TGFβ3, LEFTY A, PARP1, and ZFX are also expressed in cervical tumor samples." (PMID 31885625, 2019).
chondrosarcoma (1 paper, 2012). A malignant cartilaginous matrix-producing mesenchymal neoplasm arising from the bone and soft tissue. "In that case, elevated TGFβ3 expression in grade III chondrosarcoma compared to grade I could contribute to Smad1/5/8 activation in these tumors." (PMID 23088614, 2012). "The expression of TGFB3 and of the activin receptor-like kinase ALK2 was found to be significantly higher in grade III compared to grade I chondrosarcoma." (PMID 23088614, 2012).
Cirrhosis (1 paper, 2014). A chronic disorder of the liver in which liver tissue becomes scarred and is partially replaced by regenerative nodules and fibrotic tissue resulting in loss of liver function. "However, in the present study's ESM group, Tgfβ3, not Tgfβ1, was differentially down-regulated, the relevance of which is supported by our previous finding that the expression of Tgfβ3 was 2.6-fold higher than the Tgfβ1 expression in a CCl4-induced rat cirrhosis model for 19 wks2." (PMID 25503635, 2014).
colitis (1 paper, 2024). Inflammation of the colon. "Furthermore, the mRNA level of TGFB1 was up-regulated much higher than that of TGFB2 and TGFB3 in hUC-MSCs stimulated by MLNs homogenates from colitis mice." (PMID 38956621, 2024).
congenital cataracts (1 paper, 2011). "In the PBMCs of patients with congenital cataracts, the expression of TGFβ3 (Me=9395) was the highest and significantly greater than those of TGFβ1 (Me=4475, p=0.015, post hoc test) and TGFβ2 (Me=343, p<0.001)." (PMID 22128246, 2011).
degenerative myopia (1 paper, 2025). "Specifically, it recognized two genes within the TGF-Beta signaling pathway—TGFB3 (ENSP00000238682) and TGFB2 (ENSP00000355896)—as being associated with degenerative myopia, a connection not made by the RWR method." (PMID 40110040, 2025).
endometrial adenocarcinoma (1 paper, 2022). "Cysteine mutations in TGFB2, INHA, and INHBB associated with endometrial adenocarcinoma plus cysteine mutations in TGFB2 and TGFB3 with Loeys–Dietz syndrome lead to the hypothesis that TGFB2 is capable of heterodimerization with numerous partners." (PMID 36214621, 2022).
Ewing sarcoma (1 paper, 2025). A small round cell tumor that lacks morphologic, immunohistochemical, and electron microscopic evidence of neuroectodermal differentiation. "We also determined the expression of other TGFβ isoforms, TGFB2 and TGFB3, in the immune compartment of Ewing sarcomas and found that TGFB1 is the predominant isoform expressed." (PMID 40858520, 2025).
hypertrophic cardiomyopathy (1 paper, 2023). A condition in which the myocardium is hypertrophied without an obvious cause. "Cardiogenetic testing did not reveal a pathogenic variant in known hypertrophic cardiomyopathy genes but identified the TGFB3 p.(Asp263His) likely pathogenic variant." (PMID 37719708, 2023).
hypovitaminosis D (1 paper, 2018). "The risk factors for the development of UFs are better known than their etiology and include elevated BMI values, positive family history, genetics, black race hypovitaminosis D, soybean and food additives consumption, and elevated serum TGF-β3 (transforming growth factor beta 3) levels." (PMID 30140700, 2018).
infarction (1 paper, 2019). A localised pathological necrosis of tissue resulting from obstruction of the blood supply usually by a thrombus, an embolus, or vascular torsion. "As we showed before, TGFβ3 increased gradually with the infarction time, when the ratio of TGFβ1 to TGFβ3 changed, the inhibition of TGFβ3 predominated and the whole body experienced the inhibition effect." (PMID 30983140, 2019).
influenza (1 paper, 2021). An acute viral infection of the respiratory tract, occurring in isolated cases, in epidemics, or in pandemics; it is caused by serologically different strains of viruses (influenzaviruses) designated A, B, and C, has a 3-day incubation period, and usually lasts for 3 to 10 days. "Dietary intervention with 2′-FL significantly increased mRNA expression of TGFβ3 in a murine influenza vaccination model." (PMID 33805597, 2021).
Intervertebral Disc Degeneration (1 paper, 2024). "The predictive analysis identifies the TGFβ-1 gene as the most promising candidate associated with Intervertebral Disc Degeneration (IDD), with isoforms TGFβ-2 and TGFβ-3 also receiving prioritization." (PMID 38745993, 2024).
Intracranial Aneurysms (1 paper, 2025). "Further analysis revealed that patients with ruptured intracranial aneurysms (RIAs) exhibited significantly higher TGFB3 expression in PBMCs compared to controls." (PMID 40563991, 2025).
invasive carcinoma (1 paper, 2016). A carcinoma that is not confined to the epithelium, and has spread to the surrounding stroma. "Recently EPHB2 was found to be a target of TGFβ3-mediated invasion and migration which is in line with increased EPHB2 protein levels in invasive carcinomas." (PMID 26870995, 2016).
lentivirus infection (1 paper, 2015). Virus diseases caused by the Lentivirus genus. "When shTgfβ3 lentivirus infection was carried out, it was found to block 60% of TGFβ3 protein expression and there was a decrease in the expression of IRF6 in palatal shelves by 70%." (PMID 26240017, 2015).
long QT syndrome (1 paper, 2023). "No pathogenic variant in any of the known long QT syndrome genes was found, but she was coincidentally found to harbor the TGFB3 p.(Asp263His) variant." (PMID 37719708, 2023).
lung adenocarcinoma (1 paper, 2009). A carcinoma that arises from the lung and is characterized by the presence of malignant glandular epithelial cells. "In lung adenocarcinomas, the transcription of Tgfb3 has been suggested to be stimulated by collagen 1 through the PI3K/ERK pathway." (PMID 19426485, 2009).
metastatic cancers (1 paper, 2019). A carcinoma which has spread from the original site of growth to another anatomic site. "As with SP100 and TGFB3 as markers of Gleason score, the false negative rate for using LMNA positioning as a marker of non-metastatic cancer was high at 42.9% (3/7), and the false positive rate is relatively low at 8.3% (1/12)." (PMID 31681438, 2019). "For TGFB3 and SATB1 this difference is small, with the genes repositioned in ∼33.3% (5/15 and 6/16 respectively; false negative rate ∼66.7%) of non-metastatic cancers and 16.7% (1/6) of metastatic cancers." (PMID 31681438, 2019).
non-small cell lung carcinoma (1 paper, 2020). A group of at least three distinct histological types of lung cancer, including non-small cell squamous cell carcinoma, adenocarcinoma, and large cell carcinoma. "TRIM27 induces non-small cell lung cancer (NSCLC) cell proliferation and metastasis, and the expression of β-catenin, S100P, TGFB3, and MMP-9 were significantly inhibited by SIX3." (PMID 33264103, 2020).
oral cancer (1 paper, 2025). "Screening of the data revealed eight TRGs (TGFB3, LTBP2, BMP2, TGFB1, ACVR1, CDK9, SLC20A1, and SMURF2) with non-zero coefficients, indicating their association with the prognosis of oral cancer patients." (PMID 38698292, 2025).
osteoradionecrosis (1 paper, 2023). Necrosis of bone following radiation injury. "Despite its limitations, this study showed the encouraging effects of Anatolian propolis on bone regeneration markers BMP-2 and TGFβ-3 in a radiotherapy-induced osteoradionecrosis model." (PMID 37909529, 2023).
ovarian hyperstimulation syndrome (1 paper, 2024). A complication of ovulation induction in infertility treatment. "TGFβ1 and TGFβ3, but not TGFβ2, are upregulated in the ovaries of ovarian hyperstimulation syndrome." (PMID 38791596, 2024).
senile cataract (1 paper, 2018). A cataract with no obvious cause occurring in persons over 50 years old. "We found that the concentrations of IL-8, MMP-2, MMP-3, MMP-9, TGFβ-1, TGFβ-2, TGFβ-3, SAA, and TNF-α were significantly elevated in JIAU samples compared with the control group (senile cataract patients)." (PMID 29675026, 2018).
skin cancer (1 paper, 2018). "Runx1 acts is a tumor promoter in mouse skin cancer formation and maintenance by promoting Stat3 activation and Tgfb3 expression is often upregulated in cancer formation." (PMID 30046048, 2018).
steatosis (1 paper, 2021). Increased lipid within the cytoplasm of cells. "Eventually, we determined 10 hub genes (Down-regulated genes: MYC, TGFB3, ADAMTS1, THBS1, RASD1, PCDH20; Up-regulated genes: MAMDC4, CYP7A1, GINS2, and PDLIM3) related to NAS and steatosis." (PMID 34777484, 2021).
Stroke (1 paper, 2021). Sudden impairment of blood flow to a part of the brain due to occlusion or rupture of an artery to the brain. "In particular, let-7a can induce a significant effect on vascular function, as it appears to regulate post-stroke angiogenesis through a transforming growth factor beta 3 (TGF-β3)-dependent mechanism." (PMID 34073513, 2021).
venous insufficiency (1 paper, 2021). Impaired venous blood flow or venous return (venous stasis), usually caused by inadequate venous valves. "TGFβ3 isoform can be a product of circumferential stretch, inflammation, and matrix stiffness found in advanced stages of venous insufficiency." (PMID 34944071, 2021).
ventricular septal defect (1 paper, 2020). The presence of a defect (opening) in the septum that separates the two ventricles of the heart. "Ventricular septal defects (VSD) including the perimembranous VSDs were observed in Tgfb3−/− fetuses with myocardial defects often accompanied by the muscular type VSD." (PMID 32456345, 2020).
vitiligo (1 paper, 2020). Generalized well circumscribed patches of leukoderma that are generally distributed over symmetric body locations and is due to autoimmune destruction of melanocytes. "TGFB3, a growth factor and immune modulator, was significantly upregulated in both VKH and vitiligo." (PMID 33384688, 2020). "We suggest further studies are needed to determine the roles of TGFB3 and FLG in VKH and vitiligo." (PMID 33384688, 2020).
tumor (145 papers, 2003 to 2026). "BPA and E2 strongly induce the expression of pS2, demonstrating their estrogenic action, and concomitantly inhibiting the expression of TGFβ3, a gene associated with cellular differentiation and tumor suppression." (PMID 40061085, 2025). "We examined the association of TGFβ3/GLI2/YAP1 with tumor infiltration of various immune and immunosuppressive cells." (PMID 40027190, 2025). "Genes implicated in cell proliferation and migration such as Tgfβ3, Fzd2, Fzd9, and Lpar3 showed marked downregulation in tumor tissues post-FAA treatment." (PMID 38613073, 2024). "HOXA13, whose over-expression in UL has previously been described, is also associated with tumor size, microvascular invasion, angiogenesis, Wnt and TGFβ3 pathway in cancer." (PMID 35740301, 2022). "Significantly lower expression of TGFB3 was observed in the Basal-like tumours, which was in agreement with that the lower expression of TGFB3 was associated with ER, PR-negative tumours and that most of the Basal-like tumours were ER, PR-negative." (PMID 26703884, 2015). "Higher TGFB3 mRNA levels in the primary tumours were associated with better relapse-free survival of patients, especially for the lymph node-negative patients and in the first 3 years after diagnosis." (PMID 26703884, 2015). "The TGFB3 mRNA expression levels were around 50 % lower in the ER-negative/PR-negative/triple-negative/Basal-like/Grade 3 tumours, which were all associated with poor prognosis." (PMID 26703884, 2015). "Although iCAFs downregulated TGFB3 during treatment compared to pre-treatment, they may still promote monocyte survival and differentiation into tumor-associated macrophages by overexpressing macrophage colony-stimulating factor-1 (CSF-1)." (PMID 37833788, 2023). "By comparison, high levels of transforming growth factor beta 3 (TGFB3) mRNA expression in tumor samples was associated with significantly better survival outcomes of DIPG patients, whereas high levels of transforming growth factor beta 1 (TGFB1) expression was not prognostic." (PMID 36980562, 2023). "Therefore, we calculated the Pearson correlation between MEG3 expression and these cytokines in our tumor samples and found TGFβ3 to be the most significantly associated with MEG3 expression (Pearson’s rho = 0.74)." (PMID 36231143, 2022). "TGN treatment also decreases the secretion of TGFβ3, IL-6, and VEGF by CAF-containing tumor-like constructs, all of which facilitate tumor-associated angiogenesis, drug resistance, and metastasis." (PMID 41596251, 2026). "Studies have indicated that TGFB3 can modulate immune responses and tissue repair mechanisms, which are critical in the tumor microenvironment." (PMID 40895144, 2025). "Significant upregulation of Tgfb1, Tgfb3, and Vegfa was observed in 4T1 tumor tissues post‐irradiation." (PMID 40470716, 2025). "The first of these estrogen-regulated markers, pS2, is a well-established marker of ER activation; the second, TGFβ3, allows evaluating cellular differentiation and tumor suppressive mechanisms." (PMID 40061085, 2025). "More importantly, TGFβ3's expression significantly correlates with the level of tumor-infiltrating CAFs, suggesting it has dual roles in promoting tumorigenesis and shaping a pro-survival TME." (PMID 40027190, 2025). "Monitoring DNA methylation of TGFB1, TGFB2, and TGFB3 provides a robust method for characterizing tumor microenvironments and selecting candidates for immunotherapy in cold tumors." (PMID 40565031, 2025). "We then treated SHC1-OE-ASM and OE-Ctrl-ASM (transfected with empty vectors as the control) with TGFB3 and evaluated the tumor cell migration rates." (PMID 38360860, 2024). "Having shown that both TGFB3 overexpression and the use of recTGFβ3 significantly promoted the palbociclib response in reducing tumor growth, we sought to gain insight into the molecular mechanism by which these two drugs work together." (PMID 38831405, 2024).